BCAP31 (B cell receptor associated protein 31)
Diseases named in the same sentence as BCAP31 in open-access papers (continued):
Sharing a sentence is not in itself a finding about the gene and the disease.
cancer (35 papers, 2015 to 2025). A tumor composed of atypical neoplastic, often pleomorphic cells that invade other tissues. "Cox regression analysis across all cancer types revealed that higher BCAP31 levels were predominantly linked to worse overall survival (OS), disease-free interval (DFI), disease-specific survival (DSS), and progression-free interval (PFI)." (PMID 39737177, 2024). "B-cell receptor-associated protein 31 (BAP31) is a protein located in the endoplasmic reticulum (ER) that is involved in transporting and regulating molecules related to cell death and cancer progression." (PMID 38474195, 2024). "Third, pan-cancer research showed that BCAP31 expression was associated with immunomodulatory processes as well as immune cell infiltration." (PMID 39737177, 2024). "B-cell receptor-associated protein 31 (BAP31) has been identified to play an oncogenic role in many types of cancer." (PMID 37762705, 2023). "B-cell receptor–associated protein 31 (BAP31) has been recognized as a tumor-associated protein and has largely been shown to promote metastasis in a variety of cancers." (PMID 36895489, 2023). "B-cell receptor-associated protein 31 (BAP31) has been shown to overexpress in a wide range type of cancers." (PMID 35359416, 2022). "BAP31 (B‐cell receptor‐associated protein 31) is an important regulator of intracellular signal transduction and highly expressed in several cancer tissues or testicular tissues." (PMID 33210473, 2021). "Moreover, the BCAP31 expression levels displayed a favorable association with the ESTIMATE scores in many forms of cancer." (PMID 39737177, 2024). "In addition, we performed gene co-expression studies in order to examine the associations between the BCAP31 expression as well as immune-related genes in a sample of 33 malignancies." (PMID 39737177, 2024). "As dysregulation of EGFR is intimately associated with the oncogenesis and metastasis of different cancers 25, we hypothesized that BCAP31 promotes cancer development through regulation of the EGFR signalling pathway." (PMID 31588230, 2019). "BCAP31, recognised as a prognostic factor across various cancers, supports angiogenesis via galectin-3 upregulation." (PMID 40427675, 2025). "B-cell receptor-associated protein 31 (BAP31) is an endoplasmic reticulum-resident chaperone involved in protein transport, apoptosis, cancer biology, and lipid metabolism." (PMID 41465598, 2025). "It was shown that many prevalent pathways associated with cancer, such as DNA repair and mTORC1 signaling pathway, exhibited enrichment in several cancer types characterized by elevated levels of BCAP31." (PMID 39737177, 2024). "Subsequently, a more thorough analysis of the relationship between BCAP31 expression as well as cancer prognosis was carried out utilizing the Kaplan-Meier plot." (PMID 39737177, 2024). "BCAP31 had a positive association with immunological scores, stromal scores, and ESTIMATE ratings for the TME in the majority of human cancer types." (PMID 39737177, 2024). "Conversely, a negative correlation was observed in LAML and PCPG, which aligns with the general BCAP31 expression pattern observed in various cancer types." (PMID 39737177, 2024). "Following this, we performed an investigation into the correlation between BCAP31 as well as CNA in pan-cancer." (PMID 39737177, 2024). "In this perspective, an examination was conducted on the relationships between the levels with regards to BCAP31 expression as well as the abundance of 25 different subtypes of immune cells that infiltrate at a pan-cancer level." (PMID 39737177, 2024). "An analysis was conducted to examine BCAP31 expression across 33 distinct cancer types using TCGA-matched data." (PMID 39737177, 2024). "BCAP31 has the potential to serve as a biomarker for cancer immunology, particularly in relation to immune cell infiltration, and as an indicator of poor prognosis." (PMID 39737177, 2024).
cancer (continued). "We investigated the relationship between BCAP31 expression and tumor stage across several cancer types, ranging from stage I to stage IV." (PMID 39737177, 2024). "The outcomes regarding the correlation study showed a substantial relationship between BCAP31 expression as well as the prognosis of various cancer kinds." (PMID 39737177, 2024). "Our research’s outcomes discovered that BCAP31 possesses significance in the infiltration of immune cells into tumors across many forms of cancer." (PMID 39737177, 2024). "It has been suggested that BCAP31 regulates the migration and invasion ability of cancer cells by regulating the expressions of cytoskeletal proteins." (PMID 35813863, 2022). "Because of the limited evidence that quality-control checkpoints at the ER regulate cancer development, we focused on the functional roles and related mechanisms of BCAP31 in driving cancer development." (PMID 31588230, 2019). "Furthermore, BCAP31 expression impacted the outcomes and prognosis of cancer patients undergoing immune therapy." (PMID 39737177, 2024). "We believe this is the first pan-cancer BCAP31 investigation." (PMID 39737177, 2024). "Additionally, we examined potential relationships between BCAP31 expression and the Tumor Mutational Burden (TMB), copy number mutation, as well as immune infiltration in 33 distinct cancer types." (PMID 39737177, 2024). "Emerging evidence suggests that BCAP31 may play a role in cancer development and progression, although its specific effects across different cancer types remain incompletely understood." (PMID 39737177, 2024). "Additionally, our findings demonstrated a considerable up-regulation of BCAP31 expression in the majority of cancer cases." (PMID 39737177, 2024). "Similarly, BCAP31 expression showed a significant correlation with ESTIMATE scores across several cancer types, including DLBC, UVM, LGG, GBM, and OV." (PMID 39737177, 2024). "Notably, in some cancer types, BCAP31 expression varied significantly between earlier and later stages, suggesting a potential role for BCAP31 in tumor progression." (PMID 39737177, 2024). "BCAP31 (a member of the Bcl-2 protein family) has a potential function in cancer apoptosis, with a role in the proliferation and apoptosis of keratinocytes in cancers." (PMID 34257547, 2021). "We have found in previous studies that BCAP31 may regulate the migration and invasion ability of cancer cells by regulating the expression of cytoskeletal proteins, such as Drebrin, M-RIP, SPECC1, Nexilin, and F-actin." (PMID 32582765, 2020). "B-cell receptor-associated protein 31 (BAP31) has been identified as a cancer/testis antigen that plays an important role in promoting the development of several types of cancers via diverse molecular mechanisms." (PMID 33363167, 2020). "Unexpectedly, we identified BCAP31 as an important mediator of ligand-independent EGFR signalling to promote cancer development in TNBCs, and our study more broadly reveals that the collaboration between BCAP31 and EGFR can be exploited for therapeutic interventions." (PMID 31588230, 2019). "In order to examine the relationship between the BCAP31 expression level and prognosis, we used OS, DFI, DSS, as well as PFI as indicators to assess the prognostic implications of BCAP31 in several cancer types." (PMID 39737177, 2024). "Moreover, to examine the possible correlation between the BCAP31 expression level as well as patient survival, a comprehensive analysis of the cancer patients’ prognosis in relation to BCAP31 expression levels across all cancer types was conducted utilizing TCGA datasets." (PMID 39737177, 2024). "More interestingly, due to the high immunogenicity and specificity of CTAs in cancer, several CTAs, including CT45, BCAP31 and ACTL8, have been targeted for developing novel therapeutics against cancer." (PMID 35574342, 2022).
cancer (continued). "Our study provides pan-cancer STMN2.SIG as an outperforming approach for patient selection of immunotherapy, and advances our understanding of TAM biology and suggests potential therapeutic strategies for downregulation of BCAP31 in TAMs." (PMID 41438751, 2025). "There has not been a pan-cancer investigation into the relationship between BCAP31 and various tumors." (PMID 39737177, 2024). "Furthermore, five pairs of tumor and adjacent normal tissues from each of the three types of cancers (ESCA, LUAD and GA) exhibited higher BCAP31 expression levels in the tumor tissues compared to the adjacent normal tissues, as confirmed by IHC results." (PMID 39737177, 2024). "Additionally, we found that BCAP31 participates in the distribution of active EGFR and that the regulatory roles of BCAP31 in EGFR intracellular recycling and cancer development are RAB11-dependent." (PMID 31588230, 2019). "Consequently, we conducted in vitro co-culture experiments involving primary cancer cells, TAMs, and CD8+ T cells, demonstrating that silencing BCAP31 in TAMs results in increased cytokine production and activation of CD8+ T cells, potentially leading to immunotherapy responsiveness." (PMID 41438751, 2025). "BCAP31’s involvement in these processes suggests that it may serve as a potential therapeutic target, particularly for inhibiting metastasis in ESCA and other cancers where its expression is elevated." (PMID 39737177, 2024). "The positive correlation between BCAP31 expression and drug sensitivity to 5-Fluorouracil, ABT737, Afuresertib, AGI-5198, Alisertib, and AGI-6780 suggests that BCAP31 could serve as a predictive biomarker for the efficacy of these drugs in specific cancers." (PMID 39737177, 2024). "Moreover, C1QBP, BCAP31 and PTMS protein were predicted as their interactor pathways in cancer." (PMID 32025240, 2020).
tumor (32 papers, 2015 to 2025). "Another study identified that B cell receptor-associated protein 31 (BAP31) can promote tumor cell proliferation by stabilizing serine protease inhibitor clade E member 2 (SERPINE2), making it a potential therapeutic target for HCC." (PMID 41285707, 2025). "Through GSEA analysis and WB validation, we demonstrated that downregulation of BCAP31 in TAMs is associated with inactivation of JAK2-STAT3 signaling pathway in tumor cells." (PMID 41438751, 2025). "B-cell receptor-associated protein 31 (BAP31) has been implicated in tumor progression, but its role in angiogenesis remains unexplored." (PMID 38474195, 2024). "Dysregulated B cell receptor-associated protein 31 (BAP31) plays a crucial role in tumor progression." (PMID 38069061, 2023). "The expression of B-cell receptor associated protein 31 (BAP31) is increased in many tumor types, and it is reported to participate in proliferation, migration, and apoptosis." (PMID 37108785, 2023). "(2018), B-cell receptor-associated protein 31 (BAP31) was found to be over-expressed in CC and to play a role in promoting tumor growth and progression." (PMID 37854681, 2023). "And BCAP31 on TAMs is associated with modulation of JAK2-STAT3 pathway in tumor cells." (PMID 41438751, 2025). "BCAP31 on TAMs is associated with the modulation of JAK2-STAT3 pathway in tumor cells, indicating the BCAP31-targeted therapy in TAMs may present promising therapeutic strategies." (PMID 41438751, 2025). "Additionally, BCAP31 expression was strongly associated with the tumor microenvironment (TME), influencing the levels of infiltrating immune cells, immune-related genes, and immune-related pathways." (PMID 39737177, 2024). "Additionally, intrabodies developed against B-cell receptor-associated protein 31 (BAP31), have demonstrated caspase-dependent tumor apoptosis in vivo." (PMID 32793488, 2020). "Previous studies have indicated that B cell receptor-associated protein 31 (BAP31), a multifunctional integral protein located on the endoplasmic reticulum (ER) membrane, plays a regulatory role in modulating various molecules and participating in multiple cellular processes in tumor cells." (PMID 38069061, 2023). "Initially, an evaluation was conducted to determine the mRNA expression levels of BCAP31 within tumor samples." (PMID 39737177, 2024). "Functional assays further confirm that BCAP31 plays a critical role in promoting tumor cell migration, invasion, and proliferation." (PMID 39737177, 2024). "K-M survival curves were created, and an analysis using the Cox proportional hazards model was performed to identify the prognostic significance of BCAP31 in various tumor types." (PMID 39737177, 2024). "The raw data on BCAP31 expression in tumor and adjacent non-tumor (paracancerous) samples were obtained from the Broad Institute Cancer Cell Line Encyclopedia (CCLE) and UCSC databases." (PMID 39737177, 2024). "Western blot analysis confirmed elevated BCAP31 expression in tumor tissues compared to normal adjacent tissues, corroborating previous bioinformatic findings." (PMID 39737177, 2024). "Taken together, these results indicate that BCAP31 plays a multifaceted role in tumor progression, influencing migration, invasion, and proliferation." (PMID 39737177, 2024). "Based on the analysis of the UCSC Xena dataset, it was observed that BCAP31 exhibited differential expression across various tumor types." (PMID 39737177, 2024). "The experimental results provide compelling evidence for BCAP31’s role in tumor progression, particularly in ESCA." (PMID 39737177, 2024). "To carry out a more comprehensive examination of the influence of BCAP31 on tumor progression, we initiated a discussion on the involvement of BCAP31 in the TME." (PMID 39737177, 2024). "BCAP31-KD significantly reduced the level of pEGFR (Tyr845) in the tumours (p < 0.0001, Dunnett's test)." (PMID 31588230, 2019).
tumor (continued). "Additionally, we aimed to uncover the mechanisms by which BCAP31 influences the malignant behaviors of tumor cells." (PMID 41438751, 2025). "Through co-culture experiments, we explored how BCAP31 on TAM might affect NB tumor cells, employing NB tumor cells co-cultured with THP-1-derived macrophages where BCAP31 was specifically knocked down." (PMID 41438751, 2025). "In summary, we discovered that silencing BCAP31 in TAM could significantly inhibit the malignant behaviors of NB tumor cells in the co-culture system." (PMID 41438751, 2025). "Given that our study indicated the critical function of TEX-related TAMs in immunotherapy effectiveness, we delved deeper into their marker gene BCAP31 and explored how it might affect anti-tumor immunity." (PMID 41438751, 2025). "Collectively, we hypothesized that silencing BCAP31 in TAM could inactivate the JAK2-STAT3 signaling pathway in tumor cells, and leading to enhanced levels of pro-immune cytokines, consequently, activated CD8+ T cells." (PMID 41438751, 2025). "Our experimental results further indicated that TEX-related BCAP31+ TAMs, which are closely associated with CD8+ Tex cells, might play a role in anti-tumor immunity of NB." (PMID 41438751, 2025). "The study demonstrates that BCAP31 expression is significantly elevated in various tumor types." (PMID 39737177, 2024). "Additionally, immunohistochemistry (IHC) was performed on tumor and adjacent normal tissue samples to evaluate BCAP31 expression levels." (PMID 39737177, 2024). "This investigation can shed light on BCAP31’s function in tumor immunotherapy." (PMID 39737177, 2024). "In this article, we also found that BCAP31 may participate in the regulation of tumor cell migration and invasion through GTP metabolism and RHO signal pathway." (PMID 32582765, 2020). "These outcomes indicate a correlation between the expression levels of BCAP31 as well as the TME, which includes the immune cells’ influx of the tumor." (PMID 39737177, 2024). "By influencing tumor-infiltrating immune cells and TMB, the outcomes we discovered demonstrate that BCAP31 can be utilized as a prognostic factor for several malignancies as well as can be a key player in tumor immunity." (PMID 39737177, 2024). "Further supporting the tumor-promoting functions of BCAP31, the MTT assay demonstrated significantly reduced cell viability in BCAP31-silenced cells, reinforcing its involvement in cellular proliferation pathways." (PMID 39737177, 2024). "Our analysis examined the relationship between BCAP31 expression and various factors, including stromal score, ESTIMATE score, immune score, and tumor purity." (PMID 39737177, 2024). "Secondly, the role of BCAP31 in NB remains to be fully elucidated, as the direct intercellular mediator was not identified among tumor cells, macrophages and CD8+ T cells." (PMID 41438751, 2025). "We hypothesize that BCAP31 in TAMs may modulate JAK2-STAT3 signal in tumor cells, affecting the tumor progression." (PMID 41438751, 2025). "To explore whether reduced BCAP31 expression could enhance the cytotoxicity of CD8+ T cells in vitro, we extracted primary tumor cells from tumor samples of HLA-A2+ NB patients." (PMID 41438751, 2025). "The results showed a negative correlation between BCAP31 expression and tumor purity in patients with DLBC, UVM, LGG, and GBM." (PMID 39737177, 2024). "The observed higher BCAP31 expression in tumor tissues of ESCA, LUAD, and GA compared to corresponding normal tissues, as confirmed by immunohistochemistry, suggests that BCAP31 overexpression is a common feature across various malignancies." (PMID 39737177, 2024). "Furthermore, TNKS1BP1, AC019100.7, KRI1, BCAP31, and RP11-408E5.5 genes were significantly correlated with ESCA tumor location, lymph node metastasis, and patient age." (PMID 35813863, 2022). "Furthermore, TNKS1BP1, AC019100.7, KRI1, BCAP31, and RP11-408E5.5 were significantly correlated with ESCA tumor location, lymph node metastasis, and age of patients." (PMID 35813863, 2022).
tumor (continued). "Our data showed that the nude mice injected with shBCAP31-transfected MDA-MB-231 cells (-shBCAP31) had much smaller tumour sizes than those injected with BCAP31 cells transfected with non-target shRNA control (CTRL) or cells with re-expressed shRNA-resistant BCAP31." (PMID 31588230, 2019). "First, in prior differentially expressed gene analyses, BCAP31 was not differently expressed across OV, PCPG, and SARC tumor tissue and normal tissue." (PMID 39737177, 2024).
infection (7 papers, 2014 to 2023). The state of being infected such as from the introduction of a foreign agent such as serum, vaccine, antigenic substance or organism. "Four additional infection-induced proteolytic cleavage sites identified in BCAP31, LASP1, MISP, and TRIM28 were consistent with the sequence specificity of 3CLpro." (PMID 37240067, 2023). "This point is exemplified by our identification of the infection-induced proteolysis of BCAP31 and LASP1 from the detection of neo-C-termini." (PMID 37240067, 2023). "Moreover, an increase in TAP1 and BCAP31 mRNA was also partly observed in infected cells treated with miR-346 inhibitor, suggesting a role of miR-346 in counteracting the upregulation of these genes during infection." (PMID 29867904, 2018).
BCAP31 also shares sentences with these, for which no sentence is quoted: colon adenocarcinoma (5 papers); deafness (5); melanoma (5); neurodegenerative disease (5); ovarian carcinoma (5); liver cancer (4); cervical squamous cell carcinoma (3); glioblastoma multiforme (3); lung adenocarcinoma (3); neuroblastoma (3); osteosarcoma (3); rectum adenocarcinoma (3); virus infection (3); Alzheimer disease (2); bladder cancer (2); cerebral hypomyelination (2); cholangiocarcinoma (2); fatty liver disease (2); gastric adenocarcinoma (2); intellectual disabilities (2); Liver Dysfunction (2); liver steatosis (2); lung squamous cell carcinoma (2); lymphoma (2); Obesity (2); pancreatic adenocarcinoma (2); Parkinson disease (2); Sepsis (2); acute lung injury (1); acute myeloid leukemia (1).
A further 59 diseases each share a sentence with BCAP31 in 1 paper.